NDEL1 (nudE neurodevelopment protein 1 like 1)
Description:
Required for organization of the cellular microtubule array and microtubule anchoring at the centrosome. May regulate microtubule organization at least in part by targeting the microtubule severing protein KATNA1 to the centrosome. Also positively regulates the activity of the minus-end directed microtubule motor protein dynein. May enhance dynein-mediated microtubule sliding by targeting dynein to the microtubule plus ends. Required for several dynein- and microtubule-dependent processes such as the maintenance of Golgi integrity, the centripetal motion of secretory vesicles and the coupling of the nucleus and centrosome. Also required during brain development for the migration of newly formed neurons from the ventricular/subventricular zone toward the cortical plate. Plays a role, together with DISC1, in the regulation of neurite outgrowth. Required for mitosis in some cell types but appears to be dispensible for mitosis in cortical neuronal progenitors, which instead requires NDE1. Facilitates the polymerization of neurofilaments from the individual subunits NEFH and NEFL. Positively regulates lysosome peripheral distribution and ruffled border formation in osteoclasts (By similarity). Plays a role, together with DISC1, in the regulation of neurite outgrowth (By similarity). May act as a RAB9A/B effector that tethers RAB9-associated late endosomes to the dynein motor for their retrograde transport to the trans-Golgi network.
Synonyms: EOPA; MITAP1; NUDEL; NDE1L1; NDE2
Tractability: PROTAC: ubiquitination databases record sites on it; its protein half-life has been measured.
Gene: Protein-coding gene on chromosome 17 (8,408,528 to 8,490,411, forward strand). Ensembl gene ENSG00000166579.
Subcellular location: Cytoplasm, cytoskeleton; Cytoplasm, cytoskeleton, microtubule organizing center, centrosome; Chromosome, centromere, kinetochore; Cytoplasm, cytoskeleton, spindle
Pathways (Reactome):
Cell Cycle: Amplification of signal from unattached kinetochores via a MAD2 inhibitory signal; EML4 and NUDC in mitotic spindle formation; Mitotic Prometaphase; Resolution of Sister Chromatid Cohesion; Separation of Sister Chromatids
Signal Transduction: RHO GTPases Activate Formins
Gene Ontology:
Molecular function: identical protein binding; protein binding; microtubule binding; alpha-tubulin binding; beta-tubulin binding
Biological process: chromosome segregation; positive regulation of GTPase activity; regulation of intracellular protein transport; cell migration; centrosome localization; chromosome localization; establishment of mitotic spindle orientation; lysosome localization; microtubule nucleation; mitotic centrosome separation; positive regulation of ruffle assembly; regulation of neuron projection development; vesicle transport along microtubule; cerebral cortex radially oriented cell migration; insulin receptor signaling pathway
Cellular component: kinetochore; centrosome; cytosol; kinesin complex; axon; axon hillock; cell leading edge; cytoskeleton; microtubule associated complex; microtubule organizing center; neurofilament cytoskeleton; spindle; synaptic vesicle
Genetic constraint (gnomAD): Loss-of-function variants: 8 observed, 40.4 expected, observed/expected ratio (o/e) 0.2, 90% interval 0.12 to 0.36. The upper end of that interval is the gene's LOEUF score, 0.36, which puts it in group 1 of 6, group 1 being the genes least tolerant of losing a copy. Missense variants: 276 observed, 383.89 expected, observed/expected ratio (o/e) 0.72, 90% interval 0.65 to 0.79. Synonymous variants: 124 observed, 155.81 expected, observed/expected ratio (o/e) 0.8, 90% interval 0.69 to 0.92.
Homologues: Orthologues: chimpanzee NDEL1 (100% identical), dog NDEL1 (99% identical), macaque NDEL1 (98% identical), guinea pig NDEL1 (98% identical), pig NDEL1 (96% identical), mouse Ndel1 (96% identical), rat Ndel1 (90% identical), rabbit NDEL1 (87% identical), zebrafish ndel1b (77% identical), tropical clawed frog ndel1 (77% identical), zebrafish ndel1a (72% identical), Drosophila melanogaster nudE (34% identical), and 1 more. Paralogues in human: NDE1 (55% identical).